IGF1 (insulin like growth factor 1)
Diseases named in the same sentence as IGF1 in open-access papers (continued):
Sharing a sentence is not in itself a finding about the gene and the disease.
sarcopenia (continued). "On the other hand, genetic factors reported as sarcopenia biomarkers have also been identified such as angiotensin I-converting enzyme I (ACE), myostatin (MSTN), alpha actinin 3 (ACTN3), ciliary neurotrophic factor (CNTF), vitamin D receptor (VDR), insulin-like growth factor 1 (IGF1), and IL-6." (PMID 39194921, 2024). "However, zonulin, calprotectin and CRP were significantly elevated and IGF‐1 and irisin were significantly reduced in cirrhotic patients with sarcopenia, compared with non‐cirrhotic patients with and without sarcopenia." (PMID 37767786, 2023). "In addition, anabolic hormones such as insulin-like growth Factor1 (IGF-1) also contribute to the progression of sarcopenia and lean NAFLD, as well as non-lean NAFLD." (PMID 37424859, 2023). "Gut microbiota may also have a role in the pathogenesis of sarcopenia since short-chain fatty acids (SCFA), which are the end products of anaerobic fermentation of the intestinal microbiota, are the central modulators of IGF-1 synthesis." (PMID 36362238, 2022). "In addition to the impact of lifestyle on skeletal muscle mass and function, the present study showed that GH/IGF-1 levels were significantly different between the sarcopenia and non-sarcopenia groups." (PMID 32264885, 2020). "IGF-1 involvement in sarcopenia may not be a surprise as IGF-1 plays an important role in muscle protein synthesis and is known to decrease with age." (PMID 32517136, 2020). "Serum GDF-15, TNFα and IGF-1 levels were compared in patients with and without sarcopenia." (PMID 31581569, 2019). "Although there are several signaling pathways linked to sarcopenia, we focus our discussion on the canonical and non-canonical transforming growth factor-β (TGF-β) cascade, Wnt signaling and the insulin-like growth factor-1 (IGF-1)/Akt/mammalian target of rapamycin (mTOR) pathways." (PMID 22184279, 2011). "When exogenous myonectin supplementation is added, skeletal muscle atrophy is prevented by the AMPK α2/PGC-1α4/IGF-1-dependent pathway; however, in human trials, there were no limiting differences in serum myonectin levels among 142 older adults with or without sarcopenia." (PMID 40801027, 2025). "However, aerobic training alone could not statistically significant increase the serum IGF-1 concentration in older adults with frailty and/or sarcopenia [SMD = 0.01, 95%CI: (−0.46, 0.48), p = 0.96]." (PMID 40917423, 2025). "The observed positive correlation between IGF-1 levels and reductions in hand grip strength, appendicular lean mass, as well as whole body fat-free mass suggests that IGF-1 may serve as a potential biomarker for early detection of sarcopenia and monitoring disease progression." (PMID 39507055, 2024). "Additionally, various anabolic processes within the skeletal muscle are aided by insulin-like growth factor-1 (IGF-1), while low IGF-1 concentrations are related to skeletal muscle atrophy, suggesting that it could possibly be a key component in the development of sarcopenia." (PMID 35892736, 2022). "qRT-PCR data showed that AK treatment increased the expression of not only Pax7 (muscle stem cells, not significant) but also Igf-1 (P < 0.05), which is involved in the hypertrophy of aged muscle, thereby supporting the potential of AK as a new candidate therapeutic agent for sarcopenia." (PMID 34906228, 2021). "Therefore, increasing concentrations of circulating IGF-1 and sex hormones may be potentially beneficial for preventing sarcopenia as well as certain non-communicable diseases and conditions of aging." (PMID 32443563, 2020). "Since the IGF-1/GH axis contributes to the preservation of skeletal muscle mass, its modulation by supplementation of these hormones has been hypothesized to treat sarcopenia in older adults, but there is still no robust evidence of beneficial effects." (PMID 32911600, 2020).
sarcopenia (continued). "However, long-term administration of IGF1, even if effective, might not be an appropriate treatment for sarcopenia and cachexia because insulin-IGF1 signaling has been shown to promote cancer growth and to shorten lifespan." (PMID 24092876, 2013). "Contrary to our expectations, stool zonulin, stool calprotectin and serum LBP, sCD14, IGF‐1, myostatin, FGF‐21, irisin and DAO were comparable in cirrhotic patients with and without sarcopenia and in controls with and without sarcopenia (P > 0.05)." (PMID 37767786, 2023). "IGF-1, myostatin, and HOMA-IR levels were divided into the nonsarcopenia, sarcopenia, and severe sarcopenia groups." (PMID 35371569, 2022).
type 2 diabetes (256 papers, 2003 to 2026). "Genetic studies, including Mendelian randomization and rare genetic variants, have provided causal evidence linking elevated GH/IGF-1 signaling to cancer, type 2 diabetes, and coronary artery disease." (PMID 40574888, 2025). "Low IGF-1 levels are associated with several diseases, like type-2 diabetes mellitus (T2DM), cardiovascular diseases (CVDs), sarcopenia, osteoporosis, and frailty." (PMID 39273084, 2024). "Higher levels of IGF-1 were associated with a reduced risk of type 2 diabetes in cross-sectional and prospective epidemiological studies, but they were also associated with an increased risk in a Mendelian randomization study." (PMID 38928106, 2024). "Insulin-like growth factor 1 (IGF-1) is known to be elevated in conditions such as type 2 diabetes and cardiovascular disease, serving as a potential risk marker." (PMID 38377027, 2024). "Nevertheless, growth hormone (GH) and IGF-1 deficiency is associated with reduced rates of cancer, type 2 diabetes, and diabetic complications in humans, while increased levels of IGF-1 have been linked to the incidence of some types of cancer." (PMID 38928106, 2024). "Abnormal concentrations of IGF-1 are linked with obesity, metabolic syndrome, type 2 diabetes, atherosclerosis, heart failure (HF), and diabetic kidney disease (DKD)." (PMID 37438734, 2023). "Genetically predicted elevated levels of IGF-1, a peptide hormone similar in molecular structure to insulin, were positively associated with the risk of type 2 diabetes." (PMID 36786839, 2023). "Within the altered hormonal milieu among those with type 2 diabetes are changes in the insulin growth factor axis; recent studies have examined the role of insulin growth factor-1 (IGF-1) in the risk for complications from type 2 diabetes." (PMID 37438734, 2023). "We recently demonstrated in preclinical models that type 2 diabetes simultaneously causes resistance to IGF-1 (insulin-like growth factor-1)–mediated glucose lowering and endothelial NO release." (PMID 34420367, 2021). "Type 2 diabetes in humans and rodents is associated with whole-body and EC resistance to the actions of the closely related hormones insulin and IGF-1." (PMID 34420367, 2021). "Elevated levels of IGF-1 were linked to reduced risk of type 2 diabetes in some studies while others observed neutral effects." (PMID 33686453, 2021). "Insulinoresistance (e.g., in type 2 diabetes) or low IGF-1 levels are associated with increased β-amyloid production." (PMID 35111799, 2021). "We found that the lowest quartile of IGF-1 concentration is associated with an increased risk of type 2 diabetes at discharge among hyperglycemic ACS patients." (PMID 34851758, 2021). "The association between genetically predicted IGF-1 levels and coronary artery disease was attenuated after adjustment for type 2 diabetes (OR 1.06 [95% CI 1.00, 1.13], p = 0.063)." (PMID 32548700, 2020). "The association between IGF-1 levels and coronary artery disease appeared to be mediated, at least partly, via type 2 diabetes." (PMID 32548700, 2020). "Further research is needed to understand other possible mechanisms underlying the association between IGF-1 and type 2 diabetes." (PMID 32548700, 2020). "Another nested case–control study found that high levels of free IGF-1 were associated with higher risk of type 2 diabetes in individuals with insulin levels above the median, but with lower risk in individuals with insulin levels below the median." (PMID 32548700, 2020). "Our findings are in line with the results of two nested case–control studies, which demonstrated that high IGF-1 levels were associated with a statistically significant or a suggestive increased risk of type 2 diabetes." (PMID 32548700, 2020). "Genetically predicted IGF-1 levels were positively associated with type 2 diabetes and coronary artery disease in the primary (IVW) analysis." (PMID 32548700, 2020).
type 2 diabetes (continued). "This MR study found evidence of a causal association between increased IGF-1 levels within the normal range and higher risk of type 2 diabetes." (PMID 32548700, 2020). "Several observational studies, although not all, have reported the association of either low or high circulating total IGF-1 levels with type 2 diabetes and different cardiovascular diseases." (PMID 32548700, 2020). "Low IGF-1 levels have previously been linked with reduced insulin sensitivity, and with a higher risk of glucose intolerance and type 2 diabetes." (PMID 32655494, 2020). "Genetic predisposition to elevated serum IGF-1 levels was associated with higher risk of type 2 diabetes and coronary artery disease." (PMID 32548700, 2020). "Low IGF-1 levels were also found to be associated with the different components of metabolic syndrome, type 2 diabetes, and cardiovascular diseases." (PMID 32655494, 2020). "Here, we used the MR design to investigate the associations of long-term increased IGF-1 levels with type 2 diabetes and major cardiovascular diseases." (PMID 32548700, 2020). "This MR study showed that genetically higher IGF-1 levels were associated with increased risk of type 2 diabetes and coronary artery disease, though results for coronary artery disease were not consistent across all sensitivity analyses." (PMID 32548700, 2020). "Abnormal serum IGF-1 levels are associated with an increased risk of type 2 diabetes and cardiovascular disease." (PMID 32548700, 2020). "It has been shown that lower serum concentration of insulin-like growth factor-1 (IGF-1) is associated with an increase in type 2 diabetes." (PMID 27840328, 2017). "It has previously been shown that low concentrations of IGF-1 in the circulation increased the risk for developing type 2 diabetes considerably during a 4.5-year follow-up in 615 participants." (PMID 27769173, 2016). "More recently, another study in a case-control sample of Chinese also replicated the associations of DGKB, MADD, GLIS3, PROX1 and IGF1 with type 2 diabetes and/or glycemic traits." (PMID 21747906, 2011). "In humans, dysregulation of TGF-β signaling and the insulin/IGF-1 signaling axis have been implicated in the onset of age-associated diseases such as Type 2 Diabetes and cancer." (PMID 21533078, 2011). "Moreover, we show that post-stroke recovery in type 2 diabetes is inversely associated with peripheral IGF-1 levels." (PMID 41094027, 2026). "Metformin, a biguanide used to treat type 2 diabetes, was found to reduce the risk of dementia, cancer, and other age-related disorders by reducing insulin and IGF-1 levels, inhibiting the mTOR pathway, blocking mitochondrial function, reducing oxidative damage, and activating the AMP kinase." (PMID 39123408, 2024). "TG may also work via altering insulin-like growth factor-1 (IGF-1) and increase type 2 diabetes risk." (PMID 36624450, 2023). "However, the causal association of IGF-1 with type 2 diabetes is complex and differs by underlying molecular pathway." (PMID 36624450, 2023). "Similarly, Chinese individuals with the IGF-1 RS35767 AA genotype have reduced serum IGF-1 levels and a higher risk of type 2 diabetes." (PMID 36120463, 2022). "In addition, in the context of type 2 diabetes, studies in ob/ob mice revealed a loss of sensitivity to IGF-1 in DRG neurons." (PMID 35298717, 2022). "However, the lowest quartile of IGF-1 concentration is associated with an increased risk of type 2 diabetes." (PMID 34851758, 2021). "This study found evidence that increased IGF-1 levels may be causally associated with higher risk of type 2 diabetes." (PMID 32548700, 2020). "Furthermore, the association between genetically predicted IGF-1 levels and type 2 diabetes was consistent in sensitivity analyses based on the weighted median and MR-PRESSO methods." (PMID 32548700, 2020). "Soluble IGF2R could directly affect susceptibility to type 2 diabetes, or indirectly through growth hormone (GH) and IGF1." (PMID 25922844, 2015).
type 2 diabetes (continued). "With regard to the healing of corneal nerve and stem/progenitor cells, the topical administration of IGF-1 may become applicable in severe situations caused by persistent corneal ulcers in patients with type 2 diabetes." (PMID 24696681, 2014). "The observed increase of serum IGF-1 and insulin-to-glucose ratio indicates that sleep restriction may result in an increased risk to develop type 2 diabetes." (PMID 20414467, 2010). "Several enriched pathways, such as Type II diabetes mellitus, Integration of energy metabolism, and Peptide hormone metabolism, are associated with the hallmark of deregulated nutrient sensing, which encompasses insulin/IGF-1 signaling and metabolic dysregulation in aging." (PMID 40585135, 2025). "Thus, deletion of muscle IGF-1R is sufficient to elicit type 2 diabetes, whereas low liver production of IGF-1 is also associated with type 2 diabetes, but responsible intracellular routes are unknown." (PMID 39638246, 2024). "However, the main cluster of IGF-1-associated SNPs that were associated with a decreased risk of type 2 diabetes mapped to the growth hormone signalling pathway, possibly mediated by pleiotropic effects from fat mass, as growth hormone secretion is decreased in obesity." (PMID 36786839, 2023). "The association between IGF-1 and coronary artery disease was attenuated after adjustment for type 2 diabetes (OR 1.06 [95% CI 1.00, 1.13]), suggesting that the association may be partly mediated via type 2 diabetes." (PMID 32548700, 2020). "More than one third of these showed opposite parental influences, especially for traits related to growth (for example, IGF1 and height) and metabolism (for example, type 2 diabetes and triglyceride levels)." (PMID 40770099, 2025). "We used Mendelian randomisation to assess the effect of BMI, type 2 diabetes and IGF1 on the outcome of proteomic age acceleration." (PMID 40287427, 2025). "Epidemiological studies reveal that IGF‐1 is multifaceted and critical in aging and age‐related diseases, including cardiovascular disease, type 2 diabetes, and frailty." (PMID 40159808, 2025). "The literature reports that miR-335-3p improves type II diabetes by regulating IGF-1-mediated macrophage polarization." (PMID 40427763, 2025). "BAT transplantation also protects against both type 1 diabetes by improving glycemia with increased IGF-1 and type 2 diabetes by improving glucose tolerance with increased IL-6 or adiponectin." (PMID 40362353, 2025). "In later life, high circulating levels of IGF-1 have been associated with increased risk for several chronic diseases, including CVD, cancer, type 2 diabetes, and ADRD as well as all-cause mortality." (PMID 40574888, 2025). "For example, IGF-1 and IGF-BP3 levels were upregulated in patients with intrathyroid invasion and associated with the invasive capacity of TC, while IGF-1, IGF-BP3, and adiponectin levels with type 2 diabetes were correlated with tumor size." (PMID 39104813, 2024). "In a cross-sectional, retrospective study of 391 patients, including men over 50 and postmenopausal women with type 2 diabetes, IGF-1 was positively correlated with FN and TH BMD in men." (PMID 39398331, 2024). "We sought to investigate the association of IGF-1 and IGFBP-3 with cardio-renal outcomes among persons with type 2 diabetes." (PMID 37438734, 2023). "An important fact is that high insulin and IGF-1 play a significant role in the development of type 2 diabetes and cardiovascular diseases." (PMID 37626790, 2023). "Patients with elevated IGF-1 were younger, were more likely to be male and Black, had lower eGFR at baseline, and had a longer duration of type 2 diabetes compared to patients with lower concentrations of the biomarker." (PMID 37438734, 2023). "Levels of systemic or background IGF-1 were markedly diminished in serum of humans and animal models of type 1 and type 2 diabetes." (PMID 35298717, 2022).